CRP (C-reactive protein)
Diseases named in the same sentence as CRP in open-access papers (continued):
Sharing a sentence is not in itself a finding about the gene and the disease.
Anxiety (continued). "Inflammatory biomarkers, including increased blood C-reactive protein (CRP) and GlycA, contributed significantly to the prediction of anxiety compared to controls." (PMID 40485662, 2025). "In the multivariate logistic regression analysis, which included IL-6, CRP, ESSPRI total, ESSPRI pain, ESSPRI fatigue, and ESSDAI, only ESSPRI fatigue was identified as an independent predictor of anxiety (OR = 1.99, 95%CI: 1.12-3.53, P = 0.019)." (PMID 40822847, 2025). "A nomogram was developed incorporating six predictive factors: completion of 9 years of compulsory education, sleep disorders, anxiety, ALSFRS-R total scores, CRP levels, and SIRI values." (PMID 41018179, 2025). "Studies suggest that HIIT can lower inflammatory markers in the body, such as C-reactive protein (CRP), helping to reduce chronic low-grade inflammation, which positively influences anxiety." (PMID 40046993, 2025). "Significant improvements in TT, CRP, IL-1, VEGF, and malondialdehyde (MDA) levels; anxiety; and depressive symptoms." (PMID 37929034, 2023). "In the present study, age, CRP, Alb, Ca2+, PTH and anxiety were used as predictors to develop a prediction model for sleep disturbance in MHD patients." (PMID 35959399, 2022). "In patients with baseline hs-CRP > 5 mg/L, a monoclonal antibody drug directed at TNF-α (infliximab) can significantly reduce depressive symptoms, including depressed mood, anxiety, and suicidal ideation." (PMID 36186850, 2022). "Blood inflammatory cytokines, e.g., IL-1, IL-6, and tumor necrosis factor (TNF), their specific receptors, and acute phase reagents such as C-reactive protein (CRP), were increased in patients with anxiety." (PMID 33920547, 2021). "Significant but smaller effect sizes (0.2 ≤ d < 0.5) were found for cough, sputum, pain, anxiety, lung function parameters (VC, TLC, FEV1, PaO2, TLCO, PI max), and results of the laboratory blood tests (D-dimers, CRP)." (PMID 34501596, 2021). "The CRP level was found topartially mediate the association between C-DII and anxiety, but not for HDL-clevels [indirect effect (95% CI)] = 0.104 [0.06–0.15] for CRP)." (PMID 40110388, 2025). "Furthermore, it has been shown that exercise reduces inflammatory markers, such as C-reactive protein (CRP), interleukin-6 (IL-6), and TNF-α, thus reducing chronic inflammation-triggered anxiety symptoms." (PMID 41144483, 2025). "Through a larger production of inflammatory cytokines, including C-reactive protein and interleukin 6, visceral adipose tissue may play a significant role in the link between BAI and ABSI and anxiety and stress." (PMID 38811944, 2024). "Our findings demonstrate that those reporting myalgia, low mood, and anxiety at follow‐up had lower admission IL‐6, CRP, and ferritin respectively, than those without these symptoms in the group that survived." (PMID 37904690, 2023). "For the 3-way interactions, while CRP had a significant role in predicting chronic pain for patients with reported anxiety, this effect was much weaker for patients without anxiety." (PMID 37865679, 2023). "In comparison, for patients without anxiety or whose anxiety had not driven them to discuss with a professional, CRP gradually lost significance and became a very weak predictor of chronic pain." (PMID 37865679, 2023). "HAM-A, Hamilton Anxiety Rating Scale; CRP, C-reactive protein; SGRQ-C, St." (PMID 35371847, 2022). "Yet this effect trended in the negative direction; lower basal concentration of CRP predicted greater anxiety symptoms severity." (PMID 32272662, 2020). "Participants with anxiety also presented slightly higher BMI and CRP-values compared to those without anxiety." (PMID 29882923, 2018). "While CT-proET-1 remained a significant and independent predictor of anxiety in all these models, none of the neurohormones or the inflammation marker CRP, including their interaction terms with CT-proET-1, reached significance." (PMID 26322793, 2015).
Anxiety (continued). "Baseline characteristics of patients who withdrew and had no follow-up data had lower trait scores on the State Trait Anxiety Index and higher CRP levels but were not otherwise statistically different than those with all or some follow-up data." (PMID 25927528, 2015). "Similarly, for anxiety specifically, mediating effects were observed through WBC, platelets, neutrophils, CRP, and GlyA, with composite indices NLR, SII, SIRI, and INFLA, with intermediate ratios of 2.85, 1.40, 3.57, 3.66, 3.59, and 1.70%, 2.48, 2.05, 5.92%, respectively." (PMID 41550866, 2025). "Notably, there were no significant disparities in anxiety levels, inflammation markers like CRP, or biological indicators such as Cortisol and ACTH levels." (PMID 38040690, 2023). "Furthermore, age, CRP, Alb, Ca2+, PTH and anxiety were screened by two-way stepwise regression." (PMID 35959399, 2022). "However, CRP in the neurovegetative cluster was not significantly elevated compared to the low-grade symptomatology, p = 0.02, or the comorbid anxiety and depressive, p = 0.03, clusters at the Bonferroni corrected cut-off of p < 0.006." (PMID 35361785, 2022). "Compared with patients without mental disorders, patients with anxiety symptoms showed elevated serum vitamin A, decreased total protein and albumin (P < 0.05), elevated glycated serum protein, increased CRP (P < 0.05), and increased aspartate aminotransferase (P < 0.001)." (PMID 34007268, 2021). "Likewise, it would be useful to categorize patients before dose reduction with regard to such features as anxiety that might influence readiness to dose revert and to agree to set the decision in the context of objective measures, including BASDAI and CRP." (PMID 32793854, 2020). "This could explain why we find increased levels of several cytokines in persons with MDD and anxiety but not of CRP." (PMID 29217840, 2017). "Thus, our data support the conclusion that plasma CT-proET-1 levels predict anxiety independent of natriuretic peptides or CRP." (PMID 26322793, 2015). "Similarly, CRP also showed a negative relation to anxiety and depressive symptom severity." (PMID 32272662, 2020). "Treatment with simvastatin did not improve insomnia or anxiety symptoms in Pakistani adults with TRD and high CRP." (PMID 39359158, 2024). "In MDD patients, C3 levels were found to be related to Hamilton Rating Scale for Anxiety (HAMA) scores, although other clinical factors were not related to complement components and CRP." (PMID 37884917, 2023). "The no-training condition showed a decreased test anxiety; however, the effect size of the no-training condition was smaller than those of the MBP and CRP." (PMID 27764151, 2016). "The CRP levels made no significant contribution to predicting FAS scores at any of these time points, whilst the anxiety score was the only significant predictor at all three time points." (PMID 26599129, 2015). "Similar ICC estimates were obtained for anxiety (ICC = 0.67), perceived stress (ICC = 0.72), negative affect (ICC = 0.61), sleep disturbance (ICC = 0.58), IL-6 (ICC = 0.64), sTNF-RII (ICC = 0.73), and CRP (ICC = 0.84)." (PMID 34873150, 2021).
Crohn disease (318 papers, 2004 to 2026). A gastrointestinal disorder characterized by chronic inflammation involving all layers of the intestinal wall, noncaseating granulomas affecting the intestinal wall and regional lymph nodes, and transmural fibrosis. "Meanwhile, high baseline CRP levels are associated with an increased risk of severe disease manifestations, especially in patients with Crohn's disease, such as strictures, fistulas, and bowel perforation." (PMID 39062093, 2024). "It is also noteworthy that in inflammatory bowel diseases such as Crohn’s disease, which often involves ileocolic lesions similar to iBD, preoperative CRP levels are associated with worse postoperative outcomes and complications." (PMID 39597915, 2024). "It was reported that lower microbiome diversity is closely associated with higher level of HOMA-IR, C-reactive protein in Twins UK cohorts and higher risk of Colorectal Cancer, Crohn’s disease and irritable bowel syndrome (IBS)." (PMID 36819695, 2023). "With regard to IBD, CRP level has also been found to be significantly associated with disease activity in Crohn's disease and ulcerative colitis." (PMID 37476185, 2023). "For the ROC curves of sensitivity and diagnostic specificity of AIF-1 for Crohn’s disease severity as assessed by the HB index, we observed that the AUC was 0.66 (p = 0.014), which was very similar to that obtained with CRP (AUC = 0.69, p = 0.0066)." (PMID 35327530, 2022). "The biological inflammatory syndromes reported were generally associated with a mean CRP of 149 mg/L, which is higher than in isolated Crohn’s disease, where it is up to 50 mg/L on average at diagnosis." (PMID 35806955, 2022). "In this study, we determined a lower ADL cut‐off concentration of 6.8 mg/L to be associated with biochemical remission in Crohn's disease, using CRP and f‐calprotectin as a composite surrogate disease activity marker." (PMID 32514446, 2020). "In patients with Crohn's disease, serum adalimumab of at least 6.8 mg/L was associated with biochemical disease remission based on CRP and fecal calprotectin, supporting the use of TDM to ensure disease control." (PMID 32514446, 2020). "In CD, serum midkine levels was positively associated with Crohn's Disease Activity Index, and midkine was found to be a sensitive biomarker of diagnostic value comparable with the gold standard CRP in this disease." (PMID 27903979, 2017). "The same variant contributed to heterogeneity of effects for Crohn disease in our study, and it has been shown that this SNP is associated with levels of biomarkers other than CRP." (PMID 27327646, 2016). "However, the lack of significant findings in other studies, alongside the variability in hypomagnesemia prevalence and its association with CRP levels, indicates that the relationship between serum magnesium levels and Crohn’s disease remission is complex and not fully understood." (PMID 38892595, 2024). "On the other hand, genus Gordonibacter, associated with increased abundance in Crohn’s disease progression and closely linked to immune and inflammatory responses, aligns with our findings of an elevated correlation with Shigella infection and increased CRP levels." (PMID 38495509, 2024). "In addition, CRP levels are reportedly associated with the clinical, endoscopic, and histological disease activities in patients with inflammatory bowel disease (primarily Crohn's disease (CD))." (PMID 26839541, 2016). "A 77-year-old man with chronic iron-deficiency anemia and prior small bowel resection presented with terminal ileal ulcerations suggestive of Crohn's disease, along with elevated C-reactive protein and markedly increased fecal calprotectin." (PMID 42255762, 2026). "The only significant, positive correlation was observed between galectin-3 and CRP (r = 0.603, p < 0.05) concentrations in patients with Crohn’s disease, suggesting a potential link between galectin-3 and systemic inflammatory response in this subgroup." (PMID 41226478, 2025).
Crohn disease (continued). "Response was defined as ≥3 drop in Simple Endoscopic Score for Crohn’s Disease (SES-CD) in combination with a ≥50% reduction in C-reactive protein (CRP) and fecal calprotectin and/or a ≥3 point drop in Harvey-Bradshaw Index (HBI)." (PMID 40895558, 2025). "The next key parameter assessed was CRP, which has been reported to be more frequently elevated in children with Crohn’s disease than in those with ulcerative colitis." (PMID 40807060, 2025). "Higher fecal levels of F. prausnitzii have also been linked to lower Crohn’s Disease Activity Index (CDAI) scores, C-reactive protein (CRP) levels, and erythrocyte sedimentation rates." (PMID 40243712, 2025). "While none of the biomarkers presented a statistically significant correlation with disease activity scores in IBD patients, a notable association (r = 0.603, p < 0.05) was observed between galectin-3 and CRP levels in patients with Crohn’s disease." (PMID 41226478, 2025). "In inflammatory bowel disease (IBD), particularly Crohn’s disease, CRP levels correlate with disease activity, while in colorectal cancer (CRC), elevated CRP is associated with advanced stage and poor outcomes." (PMID 41517338, 2025). "In Crohn’s disease, baseline body weight, sex, albumin, C-reactive protein (CRP), serum creatinine, and corticosteroid use have been shown to affect drug clearance, though these factors do not significantly alter clinical drug efficacy or safety." (PMID 41226868, 2025). "Serum leucine-rich alpha-2 glycoprotein (LRG) is useful for predicting endoscopically moderate to severe Crohn’s disease when used in combination with C-reactive protein (CRP)." (PMID 39823192, 2025). "Yang and co-workers designed a biosensor platform based on CRP-affinity peptides for the precise quantification of CRP in blood samples from Crohn’s disease patients." (PMID 40862973, 2025). "During the treatment with the originator Adalimumab, among the 42 patients with Crohn’s Disease (CD), 13 had a CRP level > 5 mg/dL while 29 had a CRP level < 5 mg/dL." (PMID 39458960, 2024). "Forty children had normal high-sensitivity C-reactive protein (hs-CRP) (< 0.5 mg/L), and there was one case with concomitant Crohn’s disease where hs-CRP was 188 mg/L." (PMID 38773385, 2024). "In the group of examined patients, C-reactive protein (CRP) was more frequently elevated in patients with Crohn’s disease (74%), whereas elevated CRP was only observed in 28% of patients with ulcerative colitis." (PMID 39457188, 2024). "Several studies have shown that FC can reflect endoscopic disease activity in CD, and it is more sensitive than the Crohn’s disease activity index (CDAI) or C-reactive protein (CRP)." (PMID 38667499, 2024). "First, the enrollment criteria of CRP ≥ 1.0 mg/dL was high by the standards set in more recent Crohn’s disease trials of 0.287 mg/dL, while FCP ≥ 162.9 μg/g stool was low by those standards." (PMID 39199994, 2024). "The most extensively described biomarkers in the literature for the diagnosis of Crohn’s disease are fecal calprotectin (FC), which is a protein released by neutrophils in response to inflammation, and the serum C-reactive protein (CRP)." (PMID 38475046, 2024). "Mesenteric adipocytes secrete C-reactive protein in response to local inflammation and bacterial translocation to mesenteric fat in Crohn’s disease." (PMID 39296517, 2024). "After 8 weeks, her symptoms improved, her PCDAI (pediatric Crohn’s Disease activity index) reduced from 47.5 to 12.5, her CRP improved from 2.6 g/dL to 0.3 mg/dL and her FC reduced from <6000 μg/g to 1261 μg/g." (PMID 39339784, 2024). "Mesenteric adipocytes secrete CRP in response to local inflammation and bacterial translocation to mesenteric fat in patients with Crohn’s disease." (PMID 39296517, 2024).
Crohn disease (continued). "These authors also showed that these measurements decrease in response to medical therapy (P = 0.001), and that they correlate with clinical inflammatory markers, including C-reactive protein and the weighted Pediatric Crohn’s Disease Activity Index." (PMID 39167186, 2024). "C-reactive protein has a short half-life and elevates quickly after the onset of an inflammatory process; the performance is better in Crohn’s disease than in ulcerative colitis." (PMID 37761298, 2023). "The importance of assessing diseases such as Crohn’s disease using inflammatory markers such as CRP is highlighted by the fact that infiltrative techniques that are prone to imprecision are more commonly employed in clinical practice." (PMID 39554800, 2023). "Dkk1 is increased in the serum and intestinal mucosa of patients with Crohn’s disease, and their levels correlate with those of erythrocyte sedimentation rate and C-reactive protein." (PMID 36730179, 2023). "Although colonoscopy is the mainstay for the diagnosis of Crohn’s disease, CRP as a biomarker for Crohn’s along with Fecal Calprotectin (FCP) has been shown to reduce the need for colonoscopy and its associated complications." (PMID 39554800, 2023). "A salient contribution of CRP in tracking symptom improvement in patients with Crohn’s disease receiving infliximab was observed in a previous study." (PMID 39554800, 2023). "For instance, patients with higher albumin tend to have higher triceps skinfold measurements reflecting upper arm muscle circumference and lower hs-CRP levels in those with Crohn’s disease." (PMID 37964931, 2023). "Our data on CRP levels contrast with the results of previous studies showing elevated concentrations in Crohn’s disease patients consuming a more pro-inflammatory diet (higher DII)." (PMID 37836432, 2023). "The disease activity in Crohn’s disease (CD) and UC patients has been connected with serum levels of IL-6, soluble interleukin-2 receptor (sIL-2R), CRP, and FC values." (PMID 37710023, 2023). "To determine the effect of treatment on the inflammatory process, we measured the concentration of C-reactive protein (CRP) in the blood of patients with Crohn’s disease before and after therapy." (PMID 37892129, 2023). "Two case series reported improvement in CRP and disease activity in patients with active Crohn's disease treated with exclusive enteral nutrition as an adjuvant to aminosalicylates, immunosuppressive and/or biologic therapy." (PMID 35735908, 2023). "The FC was more sensitive than the CRP in both disease types and was more sensitive in ulcerative colitis than Crohn’s disease." (PMID 37048536, 2023). "Typical butyrate-producing bacteria Roseburia was reduced in inflammatory bowel disease and negatively correlated with CRP, contributing to the pathogenesis of ulcerative colitis and Crohn’s disease, which is consistent with our result demonstrated above." (PMID 37692165, 2023). "Researchers reported that hsa-let-7b-5p was significantly dysregulated in patients with active Crohn’s disease compared with healthy controls and was correlated with serum C-reactive protein (CRP) levels." (PMID 35633815, 2022). "First, CRP levels are significantly correlated with the proportion of corticosteroid use in patients with Crohn's disease." (PMID 35359771, 2022). "A fixed-effects IVW meta-analysis was used in the construction, and the instrument caused lower levels of TNFR1, CRP, and WBC, and it had a protective effect on ulcerative colitis and Crohn’s disease and a detrimental effect on multiple sclerosis." (PMID 36618924, 2022). "In patients with Crohn’s disease, we found positive correlations between elafin and CRP (p = 0.01; R = 0.49) and fecal calprotectin (p = 0.03; R = 0.46)." (PMID 36552023, 2022). "Seventy percent, 75% and 67% of Crohn’s disease patients in Australia and Hong Kong combined, Australia alone, and Hong Kong alone, respectively, had a CRP within the normal range (<5 mg/L)." (PMID 36079885, 2022).